AR (androgen receptor)
Diseases named in the same sentence as AR in open-access papers (continued):
Sharing a sentence is not in itself a finding about the gene and the disease.
prostate carcinoma (continued). "Thus, Yamamoto and coworkers designed ASOs able to target exon-1, intron-1 and exon-8 in AR pre-mRNA to knockdown both ARFL and AR-Vs: these ASOs suppress the growth of Enzalutamide-resistant prostate cancer cell lines and xenografts." (PMID 31366128, 2019). "Importantly, treatment with the CRBN-mediated degraders on prostate cancer cells induces a pronounced inhibitory effect on both AR and MYC signaling axes and elicited a markedly inhibitory effect on cell growth and stimulatory on cell apoptosis." (PMID 31366128, 2019). "Deregulated androgen receptor (AR) signaling is a major driver of prostate cancer." (PMID 31855178, 2019). "Remarkably, IRC117539 is also effective in inducing AR destruction and cell death in androgen-insensitive, AR-positive prostate cancer cells, which may constitute an alternative treatment strategy for CRPC." (PMID 31431473, 2019). "In combination therapies celecoxib could represent a therapeutic strategy to weaken AR/ErbB crosstalk and resistance signaling in prostate cancer progression." (PMID 31816863, 2019). "Altered AR target genes in CAFs could affect AR-mediated regulation of growth, adhesion, motility and invasion of prostate cancer cells." (PMID 30832393, 2019). "In addition, CREB3 is reported to be involved in the malignant phenotype of prostate cancer via the androgen receptor." (PMID 30940151, 2019). "This may simply reflect differences in the techniques, or it may imply the existence of cancers with incongruous AR expression and activity, analogous to “AR indifferent” prostate cancers that arise more frequently in highly-treated patients." (PMID 34926721, 2019). "Interestingly, miR-204 has an equally important role in tumorigenesis, and has been shown to be repressed by AR signaling in prostate cancer cells, but was induced by stress in animal studies." (PMID 31480771, 2019). "Additionally, it has been found to be overexpressed in prostate cancer and to regulate the androgen receptor by increasing its mRNA expression and stabilizing AR protein." (PMID 30813351, 2019). "The androgen receptor (AR) pathway plays a vital role in prostate cancer (CaP) growth." (PMID 30774773, 2019). "The inhibitory effects of RSV on androgen action in AR+ prostate cancer cells are well documented." (PMID 30832393, 2019). "Subsequent studies have revealed multiple mechanisms which may contribute to the androgen receptor-dependence in castration-resistant prostate cancer." (PMID 31552182, 2019). "We propose that AR/AR-V7 and Mnk1/2 degraders could be effective in prostate cancer patients with upregulation of AR/AR-V7 and Mnk1/2 proteins, which currently represents a pressing therapeutic challenge." (PMID 31653008, 2019). "As above-discussed, ~2% of prostate cancers at diagnosis exhibit a neuroendocrine phenotype; however, following treatment with AR pathway inhibitors, ~20–25% of patients relapse with tumors that have lost their AR dependence and have neuroendocrine features." (PMID 31366128, 2019). "Androgen/androgen receptor (AR) signaling is known to be a significant driver of prostate cancer progression, therefore androgen-deprivation therapy (ADT)—with or without anti-androgens—is often used as a standard form of care for patients with advanced and metastatic prostate cancer." (PMID 30871130, 2019). "The androgen-dependent prostate cancer cell line LNCaP is sensitive to AR inhibitors such as apalutamide and enzalutamide, making it a model system well-suited for the unbiased discovery of novel regulators of AR inhibitor sensitivity in prostate cancer cells." (PMID 31855178, 2019). "PCA3 might be used as a biomarker for the diagnosis of prostate cancer and PCGEM1 involved in c-MYC activation and androgen receptor transcriptional activation was associated with the progression of prostate cancer." (PMID 31448238, 2019).
prostate carcinoma (continued). "Importantly, PARP-associated DNA repair pathways are also closely connected to androgen receptor (AR) signaling, which is a key regulator of tumor growth and a central therapeutic target in prostate cancer." (PMID 31357527, 2019). "Previous studies have demonstrated that BRD4 can promote the transcriptional activities of oncogenic factors in prostate cancer by physically interacting with the N‐terminal domain of androgen receptor (AR), which is a crucial element of the AR signaling pathway." (PMID 30784214, 2019). "A direct consequence of these properties is that the glucocorticoid-activated GR can attenuate the biological actions of androgen-activated AR genes, suggesting an AR-dependent mechanism where GR can actually function as a tumour suppressor in cases of prostate cancer." (PMID 30717249, 2019). "However, the androgen-receptor plasticity and the adaptive mechanisms of prostate cancer cells eventually produce resistance to therapies and treatment failure." (PMID 31540293, 2019). "In prostate cancer, hypoxia activates the transcription factor androgen receptor (AR) by increasing the binding between AR and androgen responsive elements (AREs), which induces the expression of its target gene, prostate-specific antigen (PSA), and thereby regulating tumor progression." (PMID 31185618, 2019). "Nearly all prostate cancers start out as adenocarcinomas driven by the androgen receptor (AR)." (PMID 31565603, 2019). "More chromatin contact frequencies in cancer cells may facilitate to upregulate AR expression in 22Rv1 prostate cancer cells compared to RWPE1 normal cells (fold change >454.8, adj." (PMID 31515496, 2019). "Since AR plays fundamental roles in the initiation and progression of prostate cancer, TSPX might work as a modular for androgen and AR activities in the prostate." (PMID 30863497, 2019). "To better understand the genetic and biological regulatory mechanisms of prostate cancer, we conducted a meta-analysis of three major pathways i.e. androgen receptor (AR), mechanistic target of rapamycin (mTOR) and Mitogen-Activated Protein Kinase (MAPK) on prostate cancer." (PMID 31136301, 2019). "Another study indicated that curcumin analogues inhibited AR activity in prostate cancer cells." (PMID 30720759, 2019). "Thus, six biomarkers, including ERG, AMACR, SPINK1, NKX3.1, GOLM1, and AR predict higher aggressiveness of AAM than CaM prostate cancers; then, CaM had triple-negative (ERG-negative/ETS-negative/SPINK-1-negative) disease (51% vs. 35%)." (PMID 31366128, 2019). "It is important to note also that in this study it was shown that AR-V7 and AR-FL do not associate at the level of molecular complexes, suggesting that the two Ars have distinct roles in prostate cancer cells." (PMID 31366128, 2019). "AR-/NE- prostate cancers could be issued from rare AR-/NE- prostate stem cell populations present in human prostate." (PMID 31366128, 2019). "PRMT5 could also target nonhistone substrates in cancer; for example, it can methylate arginine residues on the androgen receptor (AR) in prostate cancer and regulate prostate cancer malignancy." (PMID 30922330, 2019). "Androgen receptor (AR) signaling mediates survival and progression of human prostate cancer." (PMID 31671612, 2019). "Androgen receptor modulates the expression of CD44 in prostate cancer cells." (PMID 31331331, 2019). "These compounds could be strategic adjuvants in chemotherapy by acting through complimentary mechanism to reduce cell expansion in prostate cancer, such as inhibiting AR pathway." (PMID 31671779, 2019). "In addition, AR has an impact on prostate cancer development also by affecting genomic stability and DNA repair." (PMID 31192191, 2019).
prostate carcinoma (continued). "Importantly, the GATA2 inhibitor K7174 inhibits enzalutamide-induced transcription by decreasing binding of the GATA2/AR/Mediator/Pol II transcriptional complex, contributing to sensitization of prostate cancer cells to enzalutamide treatment." (PMID 31501863, 2019). "AR is considered the oncogenic driver in prostate cancer development and progression." (PMID 30620009, 2019). "ARV-110 could degrade 95–98% of the AR in a variety of cell lines commonly used in prostate cancer studies." (PMID 31885879, 2019). "Furthermore, our study demonstrated that CDK5 and p35 are positively correlated with the in vitro and in vivo growth of prostate cancer cells through AR regulation." (PMID 31395805, 2019). "In addition to cooperating with AR to promote androgen-dependent gene expression and tumor progression, KDM4B promotes prostate cancer development through an AR-independent mechanism." (PMID 30759871, 2019). "Additionally, androgen receptor (AR) inactivation by knockdown, androgen deprivation, or treatment with bicalutamide in LNCaP cells (prostate cancer cell line) can induce telomere breaks and telomere fusion." (PMID 31416141, 2019). "HSP70 implied significant role in prostate cancer by regulating androgen receptor signaling." (PMID 30972102, 2019). "BM1-expressing prostate cancers might be sensitive to drugs targeting metabolic function, in combination with AR targeting drugs." (PMID 31366128, 2019). "Furthermore, there is some evidence that indicates the interaction between AURKA and AR in prostate cancer 14-16." (PMID 31871591, 2019). "A reciprocal negative feedback between PI3K/Akt and AR pathways has been implicated to be responsible for castration-resistant phenotype displayed in PTEN-deficient prostate cancers." (PMID 31761786, 2019). "Given the prevalent role of androgen signaling in prostate cancer initiation and progression, we generated R26hARL/wt:p16L/L: PB-Cre4 compound mice, where conditional expression of the human AR transgene and deletion of p16Ink4a co-occur in prostatic luminal epithelial cells." (PMID 30677079, 2019). "This compound also had an antiproliferative effect in the nanomolar range (IC50 0.29 ± 0.02 μM) on prostate cancer cell lines and, very interestingly, a downregulation effect on AR transcription, coupled with perturbation of some AR’s upstream transcription factors." (PMID 30682828, 2019). "For example, the expression levels of cancer-drivers/oncogenes MYC, MYB, and AR, whose roles in prostate cancer have been well established, were consistently lower in both TSPX-overexpressing LNCaP cells and TSPX-high clinical prostate cancer samples than the corresponding controls." (PMID 30863497, 2019). "This demonstrated that CDK5 may phosphorylate AR via direct biochemical interaction in prostate cancer cells by manipulation of CDK5 with overexpression, knockdown, and drug-targeted inhibition." (PMID 31395805, 2019). "Furthermore, LBCS inhibits prostate cancer viability under castration condition by repressing AR signaling." (PMID 31221168, 2019). "IHC of the prostate cancer tissues revealed the same pattern of AR and TRIM36 staining." (PMID 29449534, 2018). "Given the key role of AR for transcriptional mediation in prostate cancer, the feasibility of targeting Hsp90–Cdc37 activity to mediate AR may be useful for prostate cancer treatment." (PMID 29699578, 2018). "In addition, reactivation of the AR can occur via intratumoral production of androgens, enabling the prostate cancers to progress despite ongoing androgen deprivation." (PMID 30382692, 2018). "Together, these results indicate that CCL5 released by endothelial cells may be the essential factor to induce AR downregulation and consequently increase invasion ability of prostate cancer." (PMID 30200999, 2018). "The androgen receptor drives the growth of metastatic castration-resistant prostate cancer." (PMID 30382692, 2018).
prostate carcinoma (continued). "Additionally, based on the recently published article, it was also demonstrated that RT resulted in androgen receptor (AR) upregulation in various prostate cancer models in vitro and in vivo, providing another evidence of synergism between ADT and RT." (PMID 29320570, 2018). "The mirin effect on AR activity and cell growth suggests it might have utility as an inhibitor of prostate cancer cells." (PMID 30305041, 2018). "Androgen signal deprivation is nowadays typically achieved by AR antagonists that might also be efficient against some cases of castration-resistant prostate cancer that depend on alternative androgen metabolism." (PMID 30158439, 2018). "To elucidate the functional significance of TLX in prostate cancer growth upon androgen-deprivation stress, we then generated stable TLX-transduced clones in AR-positive prostate cancer cell lines (including LNCaP, VCaP, and LAPC-4) for in vitro and in vivo growth phenotype studies." (PMID 29555975, 2018). "Together, these results suggest that TLX may exert suppressive effect on the AR expression and its transcription activity in prostate cancer cells." (PMID 29555975, 2018). "In the present study, we demonstrated that the orphan nuclear receptor TLX, which displayed an upregulation expression in both clinical mCRPC and xenograft models, could confer androgen insensitivity in AR-positive prostate cancer cells in vitro and in vivo." (PMID 29555975, 2018). "Expression of androgen receptor (AR) in prostate cancer (PCa) is heterogeneous but the functional significance of AR heterogeneity remains unclear." (PMID 30190514, 2018). "With this, we reveal that by integrating transcriptomic, epigenetic, and AR cistromic datastreams, previously unknown prostate cancer subtypes can be found with distinct biological and clinical features." (PMID 30464211, 2018). "Androgen exposure further drives a smaller number of alternative splicing events suggesting that the AR could contribute to altered patterns of splicing in prostate cancer cells." (PMID 30271587, 2018). "Androgens act via the androgen receptor to regulate the proliferation of cells in the prostate as well as prostate cancer cells, and the effectiveness of androgen deprivation in treating prostate cancer is clear evidence for their importance in driving disease progression." (PMID 29587718, 2018). "The main therapeutic target in prostate cancer is the androgen receptor (AR)." (PMID 30352998, 2018). "The AKT and ERK pathway has been demonstrated to be required for androgen receptor (AR) activation in prostate cancer, in which PS-ITC (isothiocyanate) conjugate inhibits AKT, ERK, AR, and their downstream targets, ultimately leading to apoptosis and growth arrest in prostate cancer cells." (PMID 29346311, 2018). "Further investigation demonstrated that thestimulation of OX1R can antagonize testosterone-induced androgen receptor nuclear translocation, suggesting that orexin-A might play a role in the regulation of androgen/androgen receptor signaling in prostate cancer." (PMID 30429828, 2018). "Notably, the down-regulated processes included regulation of androgen receptor (AR) activity, which is important for pathophysiology of prostate cancer." (PMID 29568371, 2018). "Developing combination therapy for castrate-resistant prostate cancer (CRPC) may require exploiting new drug targets outside androgen receptor and PI3K / AKT / mTOR signal transduction pathways implicated in prostate cancer (PCa) progression." (PMID 30382885, 2018). "However, given that the transcriptional coactivator CBP is central to the activation of androgen receptor and NF-κB, pilot studies will be performed to test these compounds in the cellular models of prostate cancer and inflammation." (PMID 30072621, 2018). "Androgen signaling through AR has been shown to induce a DNA repair signature (32 genes) that could explain the radioresistance of some prostate cancers." (PMID 30305041, 2018).
prostate carcinoma (continued). "Additionally, it was reported that AR transactivation can be activated through IL-6 in human prostate cancer (LNCaP) cells in an androgen-independent manner." (PMID 30545141, 2018). "AR protein has been extensively investigated in prostate cancer CTCs." (PMID 30319966, 2018). "Androgens and AR also play a pivotal role in the development and progression of prostate cancer." (PMID 29721186, 2018). "Mechanistic studies have shown that niclosamide may exert its effect through degrading AR-Vs or through inhibiting other pathways, including AKT/mTOR/Pi3K, NF-κB, and Wnt-signaling, which are implicated in prostate cancer resistance and progression." (PMID 29856824, 2018). "Moreover, ELK1 inactivation resulted in strong inhibition of the growth of bladder (and prostate) cancer cells only in the presence of an activated AR." (PMID 29518027, 2018). "The majority of studies investigating the role of AR in prostate cancer have focused on its function in the malignant epithelial cells, however it is becoming increasingly apparent that androgen signalling in the stroma can also influence cancer development and progression." (PMID 29721186, 2018). "Ligand‐activated AR is well recognized as a regulator of the cyclin D‐RB axis in prostate cancer." (PMID 30108134, 2018). "The new availability of AR inhibitors such as bicalutamide, enzalutamide, and apalutamide approved for prostate cancer, suggests the possibility of their use also in AR-positive BC patients, even if AR seems to have different functions depending on BC subtypes (e.g., luminal or TN)." (PMID 29651273, 2018). "MAK (Male Germ Cell-Associated Kinase) acts as a coactivator of AR and an androgen-independent intracellular increase of MAK in prostate cancers may mediate androgen independence." (PMID 29562686, 2018). "Furthermore, several studies demonstrated that tumor suppressor genes were directly induced by androgen treatment through AR genomic action in breast and prostate cancers." (PMID 29642629, 2018). "Additionally, Tip60 played a role as a co‐activator to interact with many steroid hormone receptors, such as the androgen receptor (AR) 15, that participate in the occurrence and development of prostate cancer." (PMID 29435417, 2018). "Growth of tumor xenografts from two prostate cancer xenograft lines, LuCaP 86.2, which expresses wild-type androgen receptor (AR) and AR variant 567, and LuCaP 23.1, which expresses wild-type AR and AR variant 7, were not affected by docetaxel treatment." (PMID 29682426, 2018). "Furthermore, positive correlation of expression levels between CNPY2 and AR/AR target genes was observed in tissue samples from human prostate cancer patients." (PMID 29707137, 2018). "Based on the CNPY2 and AR expression signature in the different cell lines, we hypothesized that AR expression was regulated by CNPY2 expression in prostate cancer." (PMID 29707137, 2018). "Here the authors show AR expression heterogeneity is associated with distinct castration/enzalutamide responses and identify BCL-2 as a potential therapeutic target in castration-resistant prostate cancer." (PMID 30190514, 2018). "In addition, HDAC inhibition decreases AR full‐length and splice variant mRNA levels in the PTEN loss and SPOP mutant prostate cancer models." (PMID 29572264, 2018). "However, no systematic method is available for evaluating reference genes for either mRNA or miRNA expression in the two subtypes of prostate cancer cell lines (AR+, androgen-sensitive and AR−, androgen-insensitive)." (PMID 29386530, 2018). "Indeed, clinical intervention based on androgen deprivation therapy (ADT), which reduces AR signaling, is a cornerstone of prostate cancer treatment." (PMID 30305041, 2018).